IL37 (interleukin 37)
Diseases named in the same sentence as IL37 in open-access papers (continued):
Sharing a sentence is not in itself a finding about the gene and the disease.
systemic lupus erythematosus (30 papers, 2013 to 2025). An autoimmune multi-organ disease typically associated with vasculopathy and autoantibody production. "Increased serum IL-37 was also reported to be associated with Asian ethnicity in patients with systemic lupus erythematosus." (PMID 34367169, 2021). "However, the anti-inflammatory properties of IL-37 have been associated with inflammatory diseases, such as systemic lupus erythematosus (SLE), and inflammatory bowel disease." (PMID 30946748, 2019). "Our previous study also showed that IL-37 can inhibit PBMCs of systemic lupus erythematosus (SLE) patient to produce pro-inflammatory cytokines, and its expressions are positively associated with SLE renal disease activity." (PMID 25226272, 2014). "The MSCs overexpressing IL-37 decreased the levels of IL-1, TNF-α, IL-17, IL-6, anti-dsDNA, and anti-ANA in systemic lupus erythematosus mice." (PMID 35935954, 2022). "This study aimed to measure the peripheral blood mononuclear cells (PBMCs) and serum levels of IL-37 in patients with systemic lupus erythematosus (SLE) and to investigate its role in SLE, including its correlation with disease activity, organ disorder and the regulation of inflammatory cytokines." (PMID 24629023, 2014). "In every ELISA, positive controls were then tested alongside either murine serum samples from mice either injected with a bolus of recIL-37 or vehicle (negative control), or systemic lupus erythematosus patient serum to determine endogenous IL-37 levels." (PMID 34367169, 2021). "Elevated IL-37 levels in humans are generally found in patients with inflammatory diseases such as nonallergic asthma and systemic lupus erythematosus (SLE)." (PMID 30072596, 2018).
asthma (28 papers, 2015 to 2025). "Numerous studies have revealed a close association between the severity of asthma attacks and IL-37 levels." (PMID 41293155, 2025). "As it has been shown that asthma was associated with increased lung cancer risk, this evidence makes IL-37 as a possible inhibitor in lung cancer." (PMID 37928545, 2023). "This pattern’s significant correlation with asthma severity, exacerbations, and impaired lung function indicates that IL-37 deficiency serves as a key biomarker throughout asthma initiation, progression, and persistence, suggesting its potential functional role in disease pathogenesis." (PMID 41293155, 2025). "This implies that the loss of IL-37 function may be a part of the pathogenesis of asthma and in the majority of inflammatory diseases." (PMID 34516405, 2021). "However, the exact molecular mechanisms underlying the function of IL-37 in human asthma have yet to be fully elucidated." (PMID 29137646, 2017). "Charrad and colleagues found that IL-37 mRNA expression in serum and induced sputum was significantly lower in asthmatic patients than healthy controls, and that IL-37 mRNA expression was associated with asthma severity." (PMID 29137646, 2017). "Future research should further explore the application of IL-37 in asthma treatment and how to effectively integrate it into existing treatment plans to provide better quality of life and disease control for asthma patients." (PMID 41293155, 2025). "In a house dust mite (HDM)-induced mouse asthma model, IL-37 reduced airway eosinophil infiltration and remodelling by inhibiting IL-24-mediated EMT via modulation of STAT3 and ERK1/2 signalling." (PMID 41573715, 2025). "In a house dust mite (HDM)-induced asthma mouse model, IL-37 has demonstrated significant anti-inflammatory effects." (PMID 41293155, 2025). "Specifically, IL-37 can alleviate asthma by inhibiting Th2/Th17 immune responses, inhibiting the release of epithelial-derived alarmins (TSLP and IL-33), and attenuating airway remodeling." (PMID 41293155, 2025). "Compared with healthy controls, asthma patients exhibit a substantial increase in IL-1β and IL-33 to IL-37 expression/production ratio." (PMID 41293155, 2025). "An additional factor to consider in the context of obesity-induced airway remodeling within asthma-related inflammatory processes is the involvement of anti-inflammatory modulators, such as secretoglobin and IL-37." (PMID 38562155, 2024). "It is important to recognise that in asthma, IL-37 possesses the ability to reduce allergic inflammation by targeting not just the Th2 cytokine axis, but also all Th1/Th2/Th17 cytokine axes." (PMID 38067193, 2023). "An impaired production of IL-37 by re-stimulated T cells and reduced serum levels of IL-37 from children with asthma have been reported." (PMID 37759430, 2023). "This is in line with the finding of reduced IL-37 expression and release by nasal epithelial cells from adult asthma patients who discontinued corticosteroid therapy." (PMID 37759430, 2023). "In another airway hypersensitive state, recombined IL-37 (rIL-37) reduced airway inflammation and ameliorated asthma progression through suppressing thymic stromal lymphopoietin (TSLP) expression in lung tissues via inhibiting NF-κB and ERK1/2 pathways." (PMID 37928545, 2023). "Next, lung function results showed that both si-IL-24 and IL-37 markedly attenuated airway resistance at Mch doses of 25 and 50 mg/ml compared with the asthma model group." (PMID 36100847, 2022). "In asthma patients, the expression level of IL-37 was decreased in PBMCs relative to healthy people." (PMID 34516405, 2021). "Herein, we analyze the correlation between IL-37 and clinical features in human peripheral blood mononuclear cells (PBMCs) from 19 asthma patients and 7 health." (PMID 34516405, 2021). "Reported studies have been revealed that the level of IL-37 has been lowered in asthma patients relative to the healthy controls." (PMID 34516405, 2021).
asthma (continued). "Further, the IL-37 negatively related to Th2 cytokines in patients with asthma and allergic rhinitis, one of mechanism is through MAPK pathway." (PMID 34516405, 2021). "IL-37 is decreased in asthma and negatively related to Th2 cytokines and other pro-inflammatory cytokines." (PMID 34516405, 2021). "On the one hand, IL-37 alleviates airway inflammation and remodeling in ovalbumin -induced asthma via inhibiting the activation of NF-κB and STAT3 signalings." (PMID 34248996, 2021). "Further, IL-37 was negatively correlated with exhaled nitric oxide, asthma control test score, atopy and rhinitis history in asthmatics." (PMID 34516405, 2021). "Several studies have demonstrated that IL-37 can be a powerful cytokine to control the exacerbated inflammatory response in the airway's mucosa, as observed in asthma and allergic rhinitis." (PMID 33717074, 2021). "Recent findings suggest that IL-37 was decreased in serum and induced sputum of asthmatics, and its reduction was related to the severity of asthma." (PMID 34516405, 2021). "IL-37 expression in asthma patients with atopy history (Atopy) was lower than that without atopy history (Non-atopy)." (PMID 34516405, 2021). "The ex vivo lipopolysaccharide (LPS)-induced release of pro-inflammatory cytokines including TNF-α, IL-6, and IL-1β from asthma sputum cells was abrogated by IL-37." (PMID 29988381, 2018). "Altered IL-37 expression has been demonstrated in many inflammatory disease conditions, including asthma." (PMID 29137646, 2017). "This present review summarizes the published literature on the functions and mechanisms of IL-37 in both humans and experimental models, and explores its role in the pathophysiology of asthma." (PMID 29137646, 2017). "Recent studies using the OVA model of asthma indicate that IL-37 exerts anti-inflammatory effects in vivo and also suppresses allergen-induced AHR." (PMID 29137646, 2017). "In a murine model of asthma, local administration of IL-37 markedly reduced the degree of inflammatory cell infiltration and airway hyper-responsiveness." (PMID 29137646, 2017). "Defective IL-37 signaling can lead to both Th2- and Th1-mediated inflammatory diseases, including asthma." (PMID 29137646, 2017). "The CLARA childhood asthma study revealed reduced mRNA expression of IL-37 in children with allergic asthma and, thus, pointed toward an implication of this cytokine for human asthma pathogenesis." (PMID 27001429, 2016). "IL-37, as an anti-inflammatory cytokine, shows great promise in the treatment of asthma." (PMID 41293155, 2025). "Furthermore, by reducing NF-κB STAT3 activation, IL-37 reduced airway inflammation and reformed asthma." (PMID 41293155, 2025). "However, it has been reported that IL-37 is substantially reduced in asthmatic children, suggesting the important role of IL-37 in asthma." (PMID 39206201, 2024). "High serum periostin, TNFα, IL-4, IL-5, and the chitinase-like protein YKL-40 levels, as well as low serum IL-37 levels, were associated with exacerbated asthma in nonsmokers." (PMID 37367073, 2023). "IL-37, a novel described member of the IL-1 family, recently has been shown to curb Th2 immune response by counterbalancing IL-33, representing the potential therapeutic target in asthma." (PMID 36032162, 2022). "Similarly, IL-37 also has a protective effect in mouse models of endotoxemia, acute lung injury, and asthma when treated with rIL-37 protein." (PMID 36002836, 2022). "The underlined cascades have a role in the immune response of asthma, and IL-37 may regulate the progression of asthma through these proteins and pathways." (PMID 34516405, 2021). "Similarly, IL-37 expression of asthma patients with rhinitis (Rhinitis) was lower than that without rhinitis (Non-rhinitis)." (PMID 34516405, 2021). "In our study, we detect IL-37 mRNA of PBMCs from 19 asthma patients and 7 healthy volunteers." (PMID 34516405, 2021).
asthma (continued). "It is speculated that IL-37 as an anti-inflammatory may play a critical role in the development of asthma." (PMID 29805973, 2018). "Therefore, IL-37 is important in modulating asthma by suppressing production of pro-inflammatory cytokines." (PMID 29988381, 2018). "Despite robust evidence showing that IL-37 is an important regulator of inflammatory cell infiltration, activation, and clearance in experimental models, data on the levels and functions of IL-37 in human asthma is still limited." (PMID 29137646, 2017). "This review describes the current evidence regarding the role of IL-37 in the pathophysiology of asthma and evaluates both the potential of IL-37 as a biomarker for airway inflammation and a therapeutic target for the treatment of asthma." (PMID 29137646, 2017). "IL-37 not only interacts with inflammatory or immune cells but also with structural cells such as bronchial epithelial cells and smooth muscle cells, which are also key targets in asthma." (PMID 29137646, 2017). "IL-37 plays different roles in the pathogenesis of the different phenotypes of asthma." (PMID 29137646, 2017). "Targeting the actions of IL-37 might represent a promising strategy for the development of effective therapeutic agents against asthma." (PMID 29137646, 2017). "In addition, IL-37 levels in serum and induced sputum were lower in asthma patients compared to healthy controls and levels of IL-37 correlated with disease severity suggesting a potential protective effect." (PMID 27001429, 2016). "Moreover, it has been observed that IL-37 is downregulated in both asthma and allergic rhinitis." (PMID 38067193, 2023). "Similarly, IL-37 also appears to suppress allergic inflammation in asthma." (PMID 29137646, 2017). "Our previous work demonstrated that IL-37 alleviated airway eosinophil infiltration and airway remodeling in an HDM-induced murine asthma model." (PMID 36100847, 2022). "A murine asthma model was established by intranasal administration of house dust mite (HDM) extracts for 5 weeks, and the effects of IL-24 and IL-37 on EMT and airway remodeling were investigated by intranasal administration of si-IL-24 and rhIL-37." (PMID 36100847, 2022). "Collectively, these studies consistently indicate that IL-37 possesses the potential to mitigate airway inflammation, eosinophil infiltration, and AHR, highlighting its therapeutic potential in the alleviation of asthma symptoms." (PMID 41293155, 2025). "Meng and Zhu found that administration of recombinant human IL-37 protein, either via intranasal inhalation or intravenous injection, effectively reduced levels of IL-4, IL-5, IL-6, and IL-13 in a chronic HDM-induced asthma model." (PMID 41293155, 2025). "Overall, these results suggested that the inhibitory effect of IL-37 on the occurrence of EMT and remodeling in asthma may be related to its regulation of IL-24 levels by influencing the activation of the p-STAT3 and p-ERK1/2 signaling pathways." (PMID 36100847, 2022). "Whether the negative regulator IL-37 could exert a therapeutic effect on IL-24-mediated EMT in the bronchial epithelium, to regulate airway remodeling in asthma remains unclear." (PMID 36100847, 2022). "IL-37 attenuated the development of IL-1β, IL-6, and TNF-α in sputum cells (LPS-stimulated) in asthma patients and caused suppression of IL-17 production more notably in patients with asthma than in healthy controls." (PMID 34516405, 2021). "Further, we evaluated the correlation between the expression of IL-37 and clinical features in human PBMCs from 19 asthma patients and 7 health, which has not been clarified in previous studies." (PMID 34516405, 2021). "The level of IL-37 was lowered in patients suffering from allergic asthma relative to nonallergic asthma." (PMID 34516405, 2021).
asthma (continued). "Clinical studies have demonstrated the downregulated production of IL-37 of human PBMC in allergic asthmatics and decreased IL-37 level in induced sputum with negative correlation with disease severity of asthma." (PMID 29988381, 2018). "IL-37 can also ameliorate experimental asthma by Th2 suppression that is independent of IL-18 signaling." (PMID 29988381, 2018). "Despite the sound theoretical possibility, the role of IL-37 in asthma is still not well established." (PMID 29137646, 2017). "However, OS biomarkers NO2−, lipid peroxide, protein sulfhydrils, and inflammatory biomarkers TNFα, IL-4, IL-37, IL-1β, IL-1RL1, IL-1R1, NLRP3, and TGF-β1 showed positive association with asthma in nonsmokers, but not in smokers." (PMID 37367073, 2023). "Overall, these findings indicated that IL-37 mitigated HDM-induced airway remodeling by inhibiting IL-24-mediated EMT via the ERK1/2 and STAT3 pathways, thereby providing experimental evidence for IL-24 as a novel therapeutic target and IL-37 as a promising agent for treating severe asthma." (PMID 36100847, 2022). "On the other hand, IL-37 not only targets TSLP through NF-κB and ERK1/2 signaling pathways, but also may act on tracheobronchial epithelial cells to inhibit fibroblasts and AMSC from producing CCL11, thereby alleviating house dust mite(HDM)-induced asthma." (PMID 34248996, 2021). "In addition, the level of IL-37 was decreased in patients suffering from allergic asthma relative to nonallergic asthma patients." (PMID 34516405, 2021).
Obesity (25 papers, 2014 to 2025). Accumulation of substantial excess body fat. "In contrast, the anti-inflammatory agent IL-37 protects against obesity-associated insulin resistance by attenuating adipose tissue inflammation and increasing adiponectin levels in animal models." (PMID 41087719, 2025). "Transgenic expression of IL-37 in mice protects them from diet-induced obesity and associated metabolic complications including dyslipidemia, inflammation and insulin resistance." (PMID 30072596, 2018). "Strikingly, IL-37 expression in mice also protects against obesity and obesity-associated inflammation and insulin resistance." (PMID 30072596, 2018). "IL-37 is an anti-inflammatory cytokine of the immune system, and transgenic expression of IL-37 in mice protects them from diet-induced obesity and associated metabolic complications including dyslipidemia, inflammation and insulin resistance." (PMID 30072596, 2018). "Adverse associations of these medications with plasma IL-37 levels can be viewed in the light of evidence indicating obesity as a proinflammatory state and the fact that these medications are usually prescribed to obese diabetic patients as being weight-neutral." (PMID 36834391, 2023). "This provides strong support for an important role of the central nervous system, which contains the key sites of central appetite regulation, in obesity susceptibility and therefore highlights the importance of research into factors that influence appetite, such as IL-37." (PMID 30072596, 2018). "Interleukin-37 exerts anti-inflammatory and protective functions in many disease models, as IL-37 transgenic mice are protected against obesity-induced inflammation and insulin resistance." (PMID 38672492, 2024). "The second anti-inflammatory factor is IL-37, which serves as a crucial anti-inflammatory modulator in inflammation induced by obesity." (PMID 38562155, 2024). "Considering the pivotal roles of secretoglobin CC-16 and IL-37 as anti-inflammatory modulators, their involvement in the development of obesity-induced airway remodeling in conjunction with the inflammatory process should be acknowledged." (PMID 38562155, 2024). "In a recent study, compared with vehicle treatment, IL-37 (1μg/mouse) treatment of mice improves insulin sensitivity and ameliorates obesity-induced inflammation in adipose tissue after 22 weeks of high fat diet." (PMID 34248996, 2021). "In fact, IL-37 has been shown to ameliorate inflammation in experimental gout and to be protective against obesity-induced inflammation and insulin resistance that can lead to type II diabetes." (PMID 31936823, 2020). "IL-37-overexpressing mice showed improved response to insulin and increased glucose tolerance and were protected from obesity." (PMID 27148268, 2016). "It has been demonstrated that IL-37 has the properties of reducing obesity-induced adipose tissue inflammation and improve insulin sensitivity." (PMID 25226272, 2014). "Taken together, if frailty is present in individuals with MS, this acts suppressively to IL-37; otherwise, obesity-related MS may regulate IL-37 through the intensity of inflammatory challenges." (PMID 36834391, 2023). "IL-37 is an anti-inflammatory modulator in obesity and attenuates inflammation via the activation of AMPK signaling, decreased secretion of pro-inflammatory cytokines, decreased recruitment of pro-inflammatory cells, and attenuating the downstream pro-inflammatory signaling through TLRs in mice." (PMID 34842603, 2021). "Thus, the anti-inflammatory effects of IL-37 can alleviate established metabolic disturbances during obesity." (PMID 34248996, 2021). "In this regard, an increase expression of the cytokine IL-13, contributing to AT inflammation, has been reported to play an important role in obesity-related colon carcinogenesis, while IL-37 signaling has been described to play an inhibitory role in innate immune responses." (PMID 32714872, 2020).